LPP (LIM domain containing preferred translocation partner in lipoma)
Description:
May play a structural role at sites of cell adhesion in maintaining cell shape and motility. In addition to these structural functions, it may also be implicated in signaling events and activation of gene transcription. May be involved in signal transduction from cell adhesion sites to the nucleus allowing successful integration of signals arising from soluble factors and cell-cell adhesion sites. Also suggested to serve as a scaffold protein upon which distinct protein complexes are assembled in the cytoplasm and in the nucleus.
Tractability: Antibody: its Gene Ontology location is reachable by antibodies, with high confidence; UniProt places it where antibodies can reach, with medium confidence; the Human Protein Atlas places it where antibodies can reach. PROTAC: UniProt records ubiquitination sites on it; ubiquitination databases record sites on it; its protein half-life has been measured.
Gene: Protein-coding gene on chromosome 3 (188,152,994 to 188,890,671, forward strand). Ensembl gene ENSG00000145012.
Subcellular location: Nucleus; Cytoplasm; Cell junction; Cell membrane
Subcellular location (Human Protein Atlas): Cytosol; Focal adhesion sites; Cell Junctions; Plasma membrane
Gene Ontology:
Molecular function: protein binding
Biological process: cell-cell adhesion
Cellular component: cell junction; cytosol; focal adhesion; plasma membrane; stress fiber; anchoring junction; cytoplasm; nucleus
Genetic constraint (gnomAD): Loss-of-function variants: 34 observed, 59.15 expected, observed/expected ratio (o/e) 0.57, 90% interval 0.44 to 0.76. The upper end of that interval is the gene's LOEUF score, 0.76, which puts it in group 3 of 6, group 1 being the genes least tolerant of losing a copy. Missense variants: 896 observed, 807.22 expected, observed/expected ratio (o/e) 1.11, 90% interval 1.05 to 1.17. Synonymous variants: 328 observed, 299.71 expected, observed/expected ratio (o/e) 1.09, 90% interval 1 to 1.2.
Homologues: Orthologues: chimpanzee LPP (99% identical), macaque LPP (93% identical), dog LPP (93% identical), guinea pig LPP (90% identical), mouse Lpp (90% identical), rabbit LPP (89% identical), pig LPP (88% identical), rat Lpp (86% identical), tropical clawed frog lpp (66% identical), zebrafish lpp (62% identical). Paralogues in human: FBLIM1 (20% identical).
Diseases named in the same sentence as LPP in open-access papers:
LPP is named in the same sentence as 75 diseases in open-access papers, as found by Europe PMC text mining. Sharing a sentence is not in itself a finding about the gene and the disease. The quoted sentences say what the papers report.
lipoma (24 papers, 2009 to 2025). A benign, usually painless, well-circumscribed lipomatous tumor composed of adipose tissue. "LPP (lipoma preferred partner) gene encodes LPP protein, a member of the zyxin family of LIM domain proteins that localizes at sites of cell adhesion and cell-cell contacts 42,43." (PMID 31523167, 2019). "We found the coding sequence for miR-28-5p to be located on plus strand of chromosome 3 (chr3:188,688,781–188,688,866), within the seventh intron of LIM containing preferred translocation partner in lipoma (LPP) gene." (PMID 41441397, 2025). "Gene fusions involving LPP, the gene encoding the Lipoma Preferred Partner protein, such as a recurrent HMGA2–LPP fusion have been found in multiple tumors, including lipoma, pulmonary chondroid hamartomas, and chondromas." (PMID 34711608, 2021). "LPP (LIM domain containing preferred translocation partner in lipoma) is a member of the zyxin family of LIM proteins that is characterized as a promoter of mesenchymal/fibroblast cell migration." (PMID 32211398, 2020). "Specifically, LPP (lipoma preferred partner/LIM domain containing preferred translocation partner in lipoma), TNS3 (Tensin 3) and NR5A2 (nuclear receptor subfamily 5 group A member 2) encode proteins important in cell adhesion and migration." (PMID 30621612, 2019). "LPP (LIM domain containing preferred translocation partner in lipoma) can regulate trafficking of signaling proteins from nucleus to cytoplasm." (PMID 27901484, 2017). "PFN2 (profilin 2), BTG1 (BTG anti-proliferation factor 1), LPP (LIM domain containing preferred translocation partner in lipoma) and CDK6 (cyclin dependent kinase 6) came to prominence as significant genes that have important effects in the cancer progression." (PMID 28981542, 2017). "The 3q28 SNP (rs9815073) is an intronic variant within the LIM domain containing preferred translocation partner in lipoma gene (LPP)." (PMID 26956414, 2016). "In an attempt to link genetic expression and function to a specific CD cellular phenotype, two genes found to be related through expression studies to CD, namely LPP (lipoma-preferred partner) and ARGHAP31, have been studied in CD fibroblasts and dendritic cells, respectively." (PMID 35806180, 2022). "Among the candidate selection signal genes, the LIM domain containing the preferred translocation partner in lipoma (LPP), immunoglobulin superfamily member 11 (IGSF11), and lamin B2 (LMNB2) genes has been associated with immune responses and disease sensitivity." (PMID 34072132, 2021). "In addition to known RITA partners, such as RBP-J (recombination signal binding protein for immunoglobulin kappa J region) and LPP (lipoma-preferred partner), PRC1, NUMA1 (nuclear mitotic apparatus protein 1) and MAP1B (microtubule-associated protein 1B) were among the RITA interaction partners." (PMID 39839673, 2024). "LPP, also known as LIM domain containing preferred translocation partner in lipoma, functions in cell-cell adhesion and cell motility, but there is no report in relation to its potential role in lipid metabolism and PPL responses." (PMID 27777315, 2016). "Most of these cases were categorized as lipomas, except for one HMGA2/LPP case, which was diagnosed as ALT/WDL." (PMID 24965044, 2014).
celiac disease (11 papers, 2012 to 2024). An autoimmune genetic disorder with an unknown pattern of inheritance that primarily affects the digestive tract. "The LPP rs1464510 AC genotype showed a slightly higher risk of celiac disease in the co-dominant model (OR 1.01, CI: 0.23–4.45, p = 0.98)." (PMID 39062631, 2024). "LPP rs1464510 A allele protects from celiac disease, while the C allele increases the risk of celiac disease." (PMID 39062631, 2024). "The association between celiac disease, LPP rs1464510, and ZMIZ1 rs1250552 was further explored and quantified by odds ratio." (PMID 39062631, 2024). "For example, CTLA4 and LPP are implicated in both celiac disease and tTGA development, although the association with tTGA appears to be stronger than with celiac disease." (PMID 27015091, 2016). "LPP rs1464510 C allele increases the risk of celiac disease by 2.6 folds." (PMID 39062631, 2024). "Higher frequencies of the LPP rs1464510 AA genotype and A allele in healthy controls could be an indication that this allele and genotype play a protective role for celiac disease." (PMID 39062631, 2024). "LPP, a significant locus for LP, is reported to be associated with vitiligo and celiac disease." (PMID 38776927, 2024). "Interestingly, genetic polymorphisms in the LPP gene are potential risk factors for autoimmune diseases such as celiac disease and Addison’s diseases." (PMID 38326779, 2024). "However, in Italian families, LPP rs1464510 showed a moderate association with celiac disease." (PMID 39062631, 2024). "Statistical analysis revealed that the LPP rs1464510 A allele and the ZMIZ1 rs1250552 AG genotype reduce the risk of celiac disease by 52% and 73%, respectively." (PMID 39062631, 2024). "This study provides insights into the genetics of celiac disease in the Asian population, and it is the first study from Pakistan reporting the association of the LPP rs1464510 A allele and the ZMIZ1 rs1250552 AG genotype with the risk of celiac disease." (PMID 39062631, 2024). "The current study aimed to check the association of LPP rs1464510 C>A and ZMIZ1 rs1250552 A>G with the risk of celiac disease (CD) in the Pakistani population." (PMID 39062631, 2024). "The current study summarizes that LPP rs1464510 and ZMIZ1 rs1250552 are associated with the risk of celiac disease." (PMID 39062631, 2024). "Another study in children was able to evidence the increased risk (>90%) of developing celiac disease by the genotype of five candidate genes (SH2B3, RGS1, TAGAP, cREL, and LPP)." (PMID 32365683, 2020). "Various GWAS have proved that rs1464510 gene polymorphism in non-HLA LPP genes is a strong predictor of celiac disease in Swedish families and the US population." (PMID 39062631, 2024). "Recent GWAS of celiac disease (CD) identified 3q28 region, harbouring LIM domain containing preferred translocation partner in lipoma (LPP) gene, a gene that codes a transcriptional co-activator protein that has a role in cell to cell adhesion." (PMID 23152861, 2012). "There are 39 gene loci showing variation in Celiac Disease patients, at least four of which are known to play roles in cell–cell adhesion (LPP, C1orf106, PTPRK and PARD3), one piece of evidence suggesting a primary barrier defect may exist in Celiac Disease." (PMID 35328419, 2022).
breast carcinoma (7 papers, 2014 to 2025). "Accumulating evidence suggests that the dysregulation of LPP expression is associated with various types of cancers, such as breast cancer, myeloma and lung cancer." (PMID 30621612, 2019). "Together, loss of LPP expression or function reduces the ability of multiple breast cancer cell lines to degrade gelatin ECM." (PMID 28436416, 2017). "Nonetheless, the precise mechanisms underlying LPP phosphorylation-dependent breast cancer cell invasion remain to be elucidated." (PMID 28436416, 2017). "Consistent with our previous observations, loss of LPP was dispensable for mammary tumour growth; however, mice bearing tumours harbouring an LPP-shRNA possessed significantly fewer lung metastases when compared with mice bearing a LucA-shRNA-expressing tumours." (PMID 28436416, 2017). "To assess whether loss of LPP phosphorylation on these sites also abrogates breast cancer metastasis, we injected NMuMG-ErbB2 cells expressing a panel of LPP phospho-mutants, along with LucA-shRNA control and LPP-shRNA cells into the mammary fat pads of immunocompromised mice." (PMID 28436416, 2017). "When combined with results from previous studies examining the role of LPP in breast cancer, we believe that our results provide strong evidence indicating that MPD originates from internal breast cancer." (PMID 33371071, 2020). "Our data demonstrate a role for LPP in breast cancer cell intravasation in vivo and invadopodia formation in vitro." (PMID 28436416, 2017). "Consistent with our previous data, LPP phosphorylation is induced in TGFβ-stimulated NIC breast cancer cells." (PMID 28436416, 2017). "Using this system, we previously demonstrated that LPP promotes the in vitro migration and invasion of breast cancer cells following a TGFβ-induced EMT17." (PMID 28436416, 2017). "Our results in both human and mouse ErbB2-expressing breast cancer cells reveal that LPP co-localizes with Tks5 and actin at sites of matrix degradation, revealing that a population of cellular LPP is localized to invadopodia." (PMID 28436416, 2017). "Expression of LPP-mLIM1 and LPP-ΔABD severely impaired the ability of breast cancer cells to extravasate, when compared to NMuMG-ErbB2 cells expressing wild-type LPP (LPP-WT)." (PMID 28436416, 2017). "In the current study, we delineate an important role for LPP as a Src substrate, a positive regulator of invadopodia formation and an enhancer of breast cancer metastasis." (PMID 28436416, 2017). "Collectively, our data clearly show that LPP localizes to invadopodia structures in breast cancer cells that actively degrade matrix." (PMID 28436416, 2017). "Here the authors show that LPP is a Src-family kinase substrate that regulates the formation of protrusions of the plasma membrane -called invadopodia- required for breast cancer metastasis." (PMID 28436416, 2017). "Our data reveal that siRNA-mediated knockdown of LPP significantly reduced the area of gelatin proteolysis by HCC1954 breast cancer cells." (PMID 28436416, 2017). "IHC staining confirmed that ErbB2 was similarly expressed in lung metastatic lesions formed by LPP proficient and LPP knockdown breast cancer cells." (PMID 28436416, 2017). "We have previously demonstrated that the LIM1 domain and the α-actinin-binding domain (ABD) of LPP are important for TGFβ-mediated breast cancer migration and invasion." (PMID 28436416, 2017). "HCC1954 and NMuMG-ErbB2 breast cancer cells were stimulated with TGFβ for 24 h, plated onto Alexa 405 labelled gelatin for an additional 24 h and coverslips were fixed and stained for LPP, Tks5 and F-actin." (PMID 28436416, 2017). "We have previously demonstrated that LPP localizes to focal adhesions in response to TGFβ and this localization is critical for migration and invasion of breast cancer cells." (PMID 28436416, 2017).
breast carcinoma (continued). "Our data implicate LPP as regulator of invadopodia formation and function, performing critical roles during breast cancer cell intravasation and extravasation during the metastatic process." (PMID 28436416, 2017). "NMuMG-ErbB2 breast cancer cells harbouring LPP-shRNA and expressing eGFP-tagged LPP-WT, LPP-mLIM1 or LPP-ΔABD were intravenously injected into the CAM and monitored using high-resolution time-lapse intravital imaging." (PMID 28436416, 2017). "LPP localizes to invadopodia, along with Tks5/actin, at sites of matrix degradation and at the tips of extravasating breast cancer cells as revealed by intravital imaging of the chick chorioallantoic membrane (CAM)." (PMID 28436416, 2017). "The expression of LPP-WT, LPP-245F and LPP-C was sufficient to promote the intravasation of NMuMG-ErbB2 breast cancer cells, while the expression of LPP-D reduced the average number of detectable CTCs." (PMID 28436416, 2017). "Together, our data demonstrate that breast cancer cell extravasation and lung metastasis require LPP and an intact LIM1 and ABD." (PMID 28436416, 2017). "To assess the metastatic ability of NMuMG-ErbB2 breast cancer cells expressing different LPP phospho-mutants, we collected lung tissues at necropsy and quantified the number of macroscopic metastatic lesions." (PMID 28436416, 2017). "LPP initially localizes to the breast cancer/endothelial cell interface, precisely where the tumour cell breaches the endothelial barrier." (PMID 28436416, 2017). "The present study is the first, to our knowledge, to demonstrate that LPP is dispensable for primary mammary tumour growth but promotes metastasis of ErbB2-expressing breast cancer cells." (PMID 28436416, 2017). "In light of these observations, we assessed LPP tyrosine phosphorylation in a variety of breast cancer cell lines." (PMID 28436416, 2017). "We did not observe any differences in primary tumour growth in mice injected with NMuMG-ErbB2 or NIC breast cancer cells harbouring LPP- or LucA-shRNAs." (PMID 28436416, 2017). "IHC staining confirmed that lung metastases derived from LPP-shRNA expressing mammary tumours maintained ErbB2 levels, while exhibiting diminished LPP expression." (PMID 28436416, 2017). "Under the action of LPP, breast cancer cells may also transfer to the nipple epidermis and these high expression levels of LPP in MPD PCs may be due to its internal breast cancer." (PMID 33371071, 2020). "Finally, breast cancer cells expressing eGFP-LPP-ΔABD revealed a diffuse pattern of LPP and Tks5 expression." (PMID 28436416, 2017). "To investigate whether LPP promotes breast tumour cell intravasation in vivo, we injected NMuMG-ErbB2 and NIC breast cancer cells that possessed LucA- and LPP-shRNAs, into the mammary fat pads of immunocompromised mice." (PMID 28436416, 2017). "Finally, we show that Src-mediated LPP phosphorylation at specific tyrosine residues (Y245/301/302) is critical for invadopodia formation, breast cancer cell invasion and metastasis." (PMID 28436416, 2017). "However, our results also functionally implicate Src-mediated LPP tyrosine phosphorylation as an important determinant of its ability to promote breast cancer invasion." (PMID 28436416, 2017). "Together, these data define a previously unknown function for LPP in the formation of invadopodia and reveal a requirement for LPP in mediating the metastatic ability of breast cancer cells." (PMID 28436416, 2017). "However, LPP might also function as an oncogene by promoting metastasis, as suggested by studies on breast cancer cells in mice models." (PMID 41441397, 2025). "Thus, it is tempting to speculate that Src and PTP1B coordinately regulate the phosphorylation/dephosphorylation cycle of LPP, respectively, to enhance cellular invasion and breast cancer metastasis." (PMID 28436416, 2017).
breast carcinoma (continued). "Re-expression of LPP-WT was able to fully restore the metastatic phenotype, while mutation of LPP tyrosine residue 245 (LPP-245F) or tyrosine residues 245/297/298 (LPP-C) to phenylalanine residues did not affect the metastatic ability of breast cancer cells." (PMID 28436416, 2017). "This is in line with reduced extravasation when invadopodia components, namely CTTN, LPP and MT1-MMP, are removed from breast cancer cells." (PMID 40419795, 2025). "In breast cancer, under the stimulation of TGFB, LPP localizes to focal adhesion sites through the LIM1 domain and recruits a-actin to stimulate breast cancer cell migration and invasion, such as metastasis to the lungs." (PMID 33371071, 2020). "Invadopodia formation, breast cancer cell extravasation and metastasis require an intact LPP LIM domain and the ability of LPP to interact with α-actinin." (PMID 28436416, 2017). "Following TGFβ stimulation, we demonstrated that LPP localizes to focal adhesions via its LIM1 domain and recruits α-actinin to stress fibres as a mechanism to promote migration and invasion of mammary tumour cells." (PMID 28436416, 2017). "In 2018, one study on the epigenetic regulation of LIM family genes in different breast cancer subtypes confirmed that the putative promoter region of LIMD1 and our predicted gene LPP may be abnormally methylated in the MDA-MB435 cell line." (PMID 31480430, 2019). "We injected NMuMG-ErbB2 and NIC cells expressing a stable shRNA against LPP (LPP-shRNA) into the mammary fat pads of female immunocompromised mice, along with breast cancer cells harbouring a non-targeting shRNA control (LucA-shRNA)." (PMID 28436416, 2017). "Thus, the ability of NMuMG-ErbB2 breast cancer cells to form invadopodia and to degrade ECM is dependent on LPP expression, and moreover, relies on the presence of an intact LIM1 domain and the ABD." (PMID 28436416, 2017). "The area of lung tissue occupied by lung metastases formed by LPP knockdown breast cancer cells (+Dox-treated mice) was also significantly smaller compared to the metastatic burden produced by LPP-proficient breast cancer cells (no Dox treatment)." (PMID 28436416, 2017).